BRMS1 (BRMS1 transcriptional repressor and anoikis regulator)
Diseases named in the same sentence as BRMS1 in open-access papers (continued):
Sharing a sentence is not in itself a finding about the gene and the disease.
ovarian carcinoma (12 papers, 2009 to 2023). A malignant neoplasm originating from the surface ovarian epithelium. "In summary, we report that knockdown of BRMS1 in ovarian cancer cells is associated with upregulation of CXCR4 mediated by NF-κB activation, which then increases the metastatic potential." (PMID 22200669, 2012). "On the other hand, it has been reported that breast cancer metastasis suppressor 1 (BRMS1) inhibits metastasis in several cancer types, such as ovarian cancer, bladder cancer, melanoma, and breast cancer." (PMID 37687058, 2023). "The aim of this study was to investigate the mechanisms of BRMS1 involvement in ovarian cancer metastasis." (PMID 22200669, 2012). "We constructed a plasmid containing a short hairpin RNA (shRNA) against BRMS1 and transfected it into the ovarian cancer cell line OVCAR3." (PMID 22200669, 2012). "In this study, we employed RNA interference (RNAi) technology to knock down endogenous BRMS1 expression and analyzed the influence of BRMS1 on the metastatic behavior of ovarian cancer cells." (PMID 22200669, 2012). "To determine the effects of BRMS1 silencing on ovarian cancer cell angiogenesis, we utilized the tube formation assay." (PMID 22200669, 2012). "Previous research showed that introducing BRMS1 into the highly metastatic ovarian cancer cell line HO-8910PM significantly suppressed adhesion, motility and local invasion without affecting tumor growth in vitro." (PMID 22200669, 2012). "In this study, recombinant plasmid containing short-hairpin RNA (shRNA) sequences targeting BRMS1 mRNA transcription regions was constructed and transfected into ovarian cancer cells." (PMID 22200669, 2012). "Together, the data provide compelling evidence that BRMS1 is an effective metastasis suppressor in tumors; however, the mechanistic basis for its metastasis-suppressive function in human ovarian cancer is poorly defined." (PMID 22200669, 2012). "Consistent with results reported in the literature, we determined that BRMS1 is indeed an effective metastasis suppressor in ovarian cancer." (PMID 22200669, 2012). "Ectopic expression of BRMS1 in highly metastatic ovarian cancer cells suppresses metastasis by impairing colony formation." (PMID 23109879, 2012). "Due to the stability and long-term effectiveness of shRNA, BRMS1-shRNA was constructed and transfected into the human ovarian cancer cell line OVCAR3." (PMID 22200669, 2012). "We found that BRMS1 silencing increased adhesion, migration and invasion, and induced vascularization of ovarian cancer cells." (PMID 22200669, 2012). "The studies indicate that the BRMS1 suppressor gene may play an important role in the inhibition of ovarian cancer metastasis." (PMID 36012171, 2022). "In addition to testing the well-known hTERT promoter, we also wanted to test newly reported ovarian cancer-specific promoters Ran and Brms1." (PMID 31039796, 2019). "Cancer-specific promoters such as hTERT, hTC, Brms1, and Ran have shown promise in ovarian cancer." (PMID 31039796, 2019). "Restoration of BRMS1 function is thus a potential new strategy for treating human ovarian cancer." (PMID 22200669, 2012).
ovarian carcinoma (continued). "They further showed that transfection of BRMS1 complementary DNA (cDNA) into the highly malignant ovarian carcinoma cell line HO-8910PM significantly reduced cell adhesion, motility and invasion in vitro and also decreased the incidence of lung metastasis without affecting tumor growth." (PMID 22200669, 2012). "Therefore, we investigated the potential mechanisms of BRMS1-mediated metastasis suppression in ovarian cancer." (PMID 22200669, 2012). "Our results contribute to the better understanding of the tumor-suppressive functions of BRMS1 in ovarian cancer and suggest that BRMS1 restoration may be a promising approach for anti-metastasis therapy for human ovarian cancer." (PMID 22200669, 2012). "Because both BRMS1 and CXCR4 are involved in regulating the NF-κB signaling pathway, we hypothesized that BRMS1 might modulate metastasis of ovarian cancer cells in part by regulating CXCR4 expression." (PMID 22200669, 2012). "Therefore, we chose to perform an EMSA to explore whether BRMS1 regulates CXCR4 expression through the NF-κB pathway in ovarian cancer cells." (PMID 22200669, 2012). "Collectively, these results suggest that attenuation of BRMS1 may play a critical role in promoting migration, invasion and angiogenesis of ovarian cancer cells and BRMS1 may regulate the metastatic potential at least in part through upregulation of CXCR4 via NF-κB activation." (PMID 22200669, 2012). "It has been demonstrated that BRMS1 may be correlated with advanced ovarian cancer." (PMID 22200669, 2012). "This assumption is supported by a study where BRMS1 was demonstrated to down-regulate fascin expression in human ovarian carcinoma cell line without showing data, and concluded that this could be a potential mechanism underlying BRMS1 suppression of metastasis." (PMID 22076152, 2011).
lung carcinoma (9 papers, 2012 to 2025). "In summary, using HBEC cells with known oncogenic driver mutations as a model of lung cancer progression we show BRMS1 to be an important regulator of cell migration and invasion." (PMID 24763730, 2014). "Mutation of the E3 ligase CLD motif in BRMS1 resulted in a significant increase in lung cancer metastasis in a lung cancer mouse model." (PMID 24763730, 2014). "The current results showed that S. platensis down-regulated the expression of SHOX2 and up-regulated the expression of BRMS1 in A549 lung cancer cells." (PMID 41203700, 2025). "The S. platensis provided potential anti-proliferative effects on the A549 lung cancer cell line, such that significant up-regulations of the BRMS1 and BAX were reported." (PMID 41203700, 2025). "In lung cancer, knockdown of BRMS1 drove NSCLC cells EMT and lung metastasis via NF-κB/Twist signaling pathway, while silencing of Twist not only blocked BRMS1KD cells to undergo EMT and invasion, but also reversed the EMT process." (PMID 27613832, 2016). "S. platensis has been shown to up-regulate the expression of BRMS1 in A549 lung cancer cells, which may contribute to its anti-metastatic effect." (PMID 41203700, 2025). "Another study demonstrated BRMS1 promoter methylation of in lung cancer." (PMID 22931099, 2012). "BRMS1 was reported to be post-translationally regulated by casein kinase 2 catalytic subunit phosphorylation of nuclear BRMS1 on serine 30, leading to its export from the nucleus for degradation through 14–3-3ε mediation, which ultimately resulted in lung cancer metastasis." (PMID 38279176, 2024). "In lung cancer, p65 is known to directly recruit DNMT1 to chromatin to enhance the methylation of the BRMS1 promoter; thus, acting as a transcriptional suppressor." (PMID 34749775, 2021). "Perhaps most interestingly, BRMS1 was shown to reduce CXCR4 expression via abrogation of NF-κB signaling, which led to metastasis suppression in lung cancer cells." (PMID 22200669, 2012).
non-small cell lung carcinoma (7 papers, 2012 to 2024). A group of at least three distinct histological types of lung cancer, including non-small cell squamous cell carcinoma, adenocarcinoma, and large cell carcinoma. "Enhanced expression of BRMS1 can make non-small cell lung cancer cells sensitive to serum deprivation-induced apoptosis and increase cell viability." (PMID 39143438, 2024). "Another study determined that both BRMS1 mRNA and protein levels were diminished in non-small cell lung cancer (NSCLC) compared to the adjacent non-cancerous lung." (PMID 22200669, 2012).
gastric cancer (6 papers, 2020 to 2023). A primary or metastatic malignant neoplasm involving the stomach. "EZH2 as an upstream mediator down-regulates miRNA-125a and BRMS1 to enhance gastric cancer metastasis." (PMID 35236381, 2022). "A previous study showed that miRNA‐125b‐5p suppressed cell invasion and migration by targeting breast‐cancer metastasis suppressor 1 (BRMS1), which was found to inhibit cancer metastasis in gastric cancer cells." (PMID 32592277, 2020). "Additionally, HCG11 was verified to sponge miR-942-5p to enhance BRMS1 expression, thus affecting the biological behaviors of gastric cancer cells." (PMID 36874625, 2023). "In addition, miR-3200-5p acts as a sponge for circMTO1 and LINC00324 to attenuate tumorigenesis of gastric carcinoma and promotes osteosarcoma cell migration and invasion by negatively regulating BRMS1 expression." (PMID 35615577, 2022).
osteosarcoma (6 papers, 2020 to 2024). A usually aggressive malignant bone-forming mesenchymal neoplasm, predominantly affecting adolescents and young adults. "In a previous study, TRIM7 was reported to regulate the tumorigenesis and chemoresistance in osteosarcoma through BRMS1 ubiquitination." (PMID 38509147, 2024). "TRIM7 is upregulated in osteosarcoma tissues, promotes osteosarcoma cell migration and invasion by mediating the ubiquitination of breast cancer metastasis inhibitor 1 (BRMS1), and contributes to chemotherapy resistance." (PMID 36249749, 2022). "miR-3200-5p is a key factor that enhances the invasiveness of osteosarcoma cells by regulating the level of BRMS1 protein." (PMID 33149754, 2020).
bladder cancer (5 papers, 2012 to 2024). "The results of other studies suggest that BRMS1 also suppresses metastasis in ovarian carcinoma and human bladder cancers." (PMID 24688598, 2014). "BRMS1 expression has also been shown to be lower in a highly metastatic human bladder carcinoma cell line (T24T) than in the less metastatic T24 parental cell line." (PMID 22931099, 2012). "In prostate and bladder cancer cells, systemic SPHK1/S1P signal through SiPR2 promotes lung metastasis via repressing the breast cancer metastasis suppressor 1 (BRMS1)." (PMID 39063133, 2024).
breast tumor (4 papers, 2012 to 2017). "BRMS1 promoter methylation was evaluated as a prognostic biomarker in primary breast tumors and a subset of corresponding circulating tumor cells." (PMID 25961669, 2015).
glioma (3 papers, 2021 to 2024). A benign or malignant brain and spinal cord tumor that arises from glial cells (astrocytes, oligodendrocytes, ependymal cells). "The underlying mechanisms of BRMS1 in gliomas remain to be fully elucidated and represent a promising focus for future research." (PMID 39143438, 2024). "Subsequently, to demonstrate that BRMS1 expressed in microglia plays a key role in the glioma microenvironment and can alter the proliferation and invasive capabilities of glioma cells, we conducted in vitro functional experiments." (PMID 39143438, 2024). "An interesting future experiment to further determine the expression patterns in different cell types of glioma tissue would be double fluorescence staining with BRMS1 and cell-type-specific markers, such as IDH1R132H, NeuN, GFAP, or CD68." (PMID 37296870, 2023). "BRMS1 protein expression in gliomas appeared to be primarily influenced by post-transcriptional processes." (PMID 37296870, 2023). "Still, the changes in behavior modulated by BRMS1 across different entities (e.g., affecting invasion, migration, and apoptosis) closely resemble the changes seen in gliomas." (PMID 37296870, 2023). "BRMS1 mRNA was overexpressed in gliomas grade 2/3 compared to NB (p < 0.01, mean 8.9 fold), PA (p < 0.01, mean 8.3 fold), and GBM (p < 0.01, mean 6.0 fold)." (PMID 37296870, 2023). "The steps regulated by BRMS1, such as invasion, migration, and apoptosis, are commonly dysregulated in gliomas." (PMID 37296870, 2023). "Our analyses present the first data on BRMS1 expression in gliomas that can provide a starting point for further investigations." (PMID 37296870, 2023). "Further, these authors showed that BRMS1 suppressed glioma invasion, migration, and adhesion in cell culture experiments and suggested BRMS1 as a potential future therapeutic target." (PMID 37296870, 2023). "RNA sequencing and microarray data from other publicly available datasets analyzed via the GlioVis data portal confirmed BRMS1 overexpression in gliomas compared to NB." (PMID 37296870, 2023). "Both stRNA-seq and scRNA-seq indicate that BRMS1 + microglia may promote the malignant transformation of glioma cells through SPP1/CD44-mediated intercellular interactions." (PMID 39143438, 2024). "As gliomas rarely metastasize, BRMS1 has mainly been neglected in glioma research." (PMID 37296870, 2023). "Interestingly, gliomas grade 2/3, the examined malignant tumor type with the comparably best prognosis and most prolonged OS, also displayed the strongest BRMS1 mRNA and protein expression." (PMID 37296870, 2023). "So far, only a few publications have addressed BRMS1 in gliomas." (PMID 37296870, 2023). "Therefore, BRMS1 shows potential as a regulator of glioma behavior, and we present the first insights into BRMS1 expression in gliomas as a starting point for further investigations." (PMID 37296870, 2023). "Gliomas grade 2/3 had significant BRMS1 overexpression compared to NB, PA, and GBM." (PMID 37296870, 2023). "Interestingly, however, we could also observe multiple BRMS1-positive glioma grade 2/3 cells, whereas tumor cells in GBM and normal astrocytes in the cerebellum/cerebrum rarely displayed strong BRMS1 expression." (PMID 37296870, 2023). "Therefore, BRMS1 shows potential as a regulator of glioma behavior." (PMID 37296870, 2023). "However, data on BRMS1 in patients’ gliomas is still scarce." (PMID 37296870, 2023). "Additionally, BRMS1’s interaction partners are commonly dysregulated in gliomas." (PMID 37296870, 2023). "In our bioinformatics research and subsequent cell experiments, upregulation of BRMS1 in HMC3 cells promoted the proliferation, migration, and invasion of glioma cells, and inhibited apoptosis." (PMID 39143438, 2024). "Therefore, the hypothesis of BRMS1 being associated with glioma patients’ survival should not be completely discarded, though our subgroup analyses indicate otherwise." (PMID 37296870, 2023).
glioma (continued). "As BRMS1 protein expression in all examined tumor subgroups except for gliomas grade 2/3 appeared to be small to nonexistent, one might argue that expression differences did not matter as they were similarly low." (PMID 37296870, 2023). "Expression in glioma grade 2/3 cells was intermediate, whereas GBM cells expressed little to no BRMS1." (PMID 37296870, 2023). "We analyzed BRMS1 mRNA expression of 12 non-cancerous brain (NB) specimens (autopsy = 8; epilepsy surgery = 4), four patients with benign adult pilocytic astrocytoma WHO grade 1 (PA), 24 astrocytomas IDH mutant, CNS WHO grades 2 and 3 (in the following referred to as gliomas grade 2/3) and 78 GBM." (PMID 37296870, 2023).
hepatocellular carcinoma (3 papers, 2012 to 2024). A malignant tumor that arises from hepatocytes. "However, the role of BRMS1 in hepatocellular carcinoma (HCC) remains elusive." (PMID 22927944, 2012). "As a function effector of tumor metastasis suppressor factor (BRMS1), SCIN plays a regulatory role in the apoptosis of hepatocellular carcinoma cells." (PMID 39108273, 2024).
lymph node metastasis (3 papers, 2012 to 2017). "BRMS1 was hypothesized to be associated with lymph node metastasis, which is usually correlated with distant metastasis." (PMID 22931099, 2012). "BRMS1 was correlated with surgical stage, lymph node metastasis and tumor size." (PMID 22200669, 2012).
metastatic melanoma (3 papers, 2012). A melanoma that has spread from its primary site to another anatomic site. "Thus, it may be speculated that benign nevi and primary and metastatic melanomas express different BRMS1 variants with different biological functions." (PMID 22356677, 2012). "A significantly higher percentage of benign nevi (87%) as compared to primary (20%) and metastatic melanoma (48%), expressed BRMS1 in the nucleus (p < 0.0001)." (PMID 22356677, 2012). "The goal was to measure BRMS1 expression in benign nevi, primary and metastatic melanomas and evaluate its impact on disease progression and prognosis." (PMID 22356677, 2012).
dysplastic nevi (2 papers, 2012). "Thus, it may be speculated that loss of nuclear BRMS1 expression is an early event, distinguishing common and dysplastic nevi." (PMID 22356677, 2012).
epilepsy (2 papers, 2023 to 2026). A brain disorder characterized by episodes of abnormally increased neuronal discharge resulting in transient episodes of sensory or motor neurological dysfunction, or psychic dysfunction. "NB specimens obtained from autopsies and epilepsy surgery had similar BRMS1 mRNA expression (p > 0.05)." (PMID 37296870, 2023).
nasopharyngeal carcinoma (2 papers, 2012 to 2021). A carcinoma arising from the nasopharyngeal epithelium. "Besides that, miR-346 has been demonstrated to promote migration and invasion of nasopharyngeal carcinoma cells via targeting BRMS1." (PMID 34054958, 2021). "This study aimed to investigate the impact of BRMS1 on metastasis in nasopharyngeal carcinoma (NPC) and to evaluate the prognostic significance of BRMS1 in NPC patients." (PMID 22931099, 2012).
triple-negative breast carcinoma (2 papers, 2017 to 2022). An invasive breast carcinoma which is negative for expression of estrogen receptor (ER), progesterone receptor (PR), and human epidermal growth factor receptor 2 (HER2). "The decreased expression of breast cancer metastasis suppressor gene 1 (BRMS1) in triple-negative breast cancer (TNBC) is related to DNA methylation modification, and demethylation can reactivate BRMS1 expression to inhibit cell invasion." (PMID 35132081, 2022).
asthma (1 paper, 2022). "This information supports that the regulation of RIN1 and BRMS1 is involved in the disease progression of asthma via allelic variations in rs117996675." (PMID 35432474, 2022).
astrocytomas (1 paper, 2023). "By bioinformatic analysis, in addition to our cohort of 118 specimens, we determined BRMS1 mRNA and protein expression as well as its correlation with the clinical course in astrocytomas IDH mutant, CNS WHO grade 2/3, and glioblastoma IDH wild-type, CNS WHO grade 4." (PMID 37296870, 2023).
benign ovarian tumor (1 paper, 2012). "Furthermore, Zhao and Wang observed that BRMS1 expression in ovarian serous adenocarcinoma was significantly lower than in both normal ovarian tissue and benign ovarian tumor tissue." (PMID 22200669, 2012).
cutaneous melanoma (1 paper, 2014). A primary melanoma arising from atypical melanocytes in the skin. "However, although the mRNA and protein expression findings are interesting, mRNA and protein levels for BRMS1 do not always correlate, at least in cutaneous melanoma." (PMID 24688598, 2014).
endometrial disorder (1 paper, 2018). A non-neoplastic or neoplastic disorder that affects the endometrium. "No relevant studies focus on the relationship of Entpd1, Fam50a, and Brms1 to endometrial disorders, and further studies are needed." (PMID 30322386, 2018).
Fibroadenoma (1 paper, 2017). A benign tumor of the breast characterized by the presence of stromal and epithelial elements. "BRMS1 promoter methylation was detected neither in 29 non-cancerous breast tissues nor in the 10 fibroadenoma samples tested." (PMID 29069768, 2017).